ZNF503 (zinc finger protein 503)
Description:
May function as a transcriptional repressor.
Synonyms: NOLZ1; ZPO2; ZEPPO2; FLJ45745; MGC2555; Nlz2; NOLZ-1
Tractability: Antibody: the Human Protein Atlas places it where antibodies can reach. PROTAC: ubiquitination databases record sites on it.
Gene: Protein-coding gene on chromosome 10 (75,397,830 to 75,401,764, reverse strand). Ensembl gene ENSG00000165655.
Subcellular location: Nucleus
Subcellular location (Human Protein Atlas): Cytosol; Plasma membrane; Nucleoplasm
Gene Ontology:
Molecular function: protein binding
Biological process: G1 to G0 transition involved in cell differentiation; negative regulation of cell population proliferation; negative regulation of gene expression; negative regulation of DNA-templated transcription
Cellular component: nucleus
Genetic constraint (gnomAD): Loss-of-function variants: 14 observed, 21.27 expected, observed/expected ratio (o/e) 0.66, 90% interval 0.43 to 1.03. The synonymous counts are far from expectation, so gnomAD's model fits this gene poorly and the ratio says little. Missense variants: 939 observed, 793.04 expected, observed/expected ratio (o/e) 1.18, 90% interval 1.12 to 1.25. Synonymous variants: 530 observed, 398.71 expected, observed/expected ratio (o/e) 1.33, 90% interval 1.24 to 1.43.
Homologues: Orthologues: macaque ZNF503 (99% identical), chimpanzee ZNF503 (99% identical), dog ZNF503 (98% identical), pig ZNF503 (98% identical), mouse Zfp503 (96% identical), rat Zfp503 (96% identical), rabbit ZNF503 (92% identical), zebrafish znf503 (70% identical), tropical clawed frog znf503 (62% identical), guinea pig ZNF503 (51% identical), Drosophila melanogaster noc (24% identical), Drosophila melanogaster elB (22% identical), and 1 more. Paralogues in human: ZNF703 (52% identical).
Diseases named in the same sentence as ZNF503 in open-access papers:
ZNF503 is named in the same sentence as 16 diseases in open-access papers, as found by Europe PMC text mining. Sharing a sentence is not in itself a finding about the gene and the disease. The quoted sentences say what the papers report.
breast cancer (4 papers, 2020 to 2024). A primary or metastatic malignant neoplasm involving the breast. "ZNF503 inhibits GATA3 expression, a key regulator of mammary LEP differentiation, and its downregulation is associated with aggressive breast cancers." (PMID 39545637, 2024). "Previously, a focal deletion was found in zinc finger protein 503 in dogs with mammary tumours." (PMID 32857815, 2020).
colon cancer (2 papers, 2019 to 2024). "AEBP1 and ZNF503 have not been previously related with PAH pathogenesis, and both were identified as common overregulated genes in colon cancer, suggesting their importance in the establishment of tumoral processes." (PMID 39791702, 2024).
Huntington disease (1 paper, 2023). Huntington disease (HD) is a rare neurodegenerative disorder of the central nervous system characterized by unwanted choreatic movements, behavioral and psychiatric disturbances and dementia. "In addition, the changes in the protein NRXN3 level in the brain cerebrospinal fluid derived from Huntington’s disease agreed with the protein and mRNA levels of ZNF503." (PMID 38049855, 2023).
lung carcinoma (1 paper, 2019). "ZNF503, important for development of the brain, was found to contribute to development and progression of breast, colon, and lung cancers through transcriptional regulation of different genes." (PMID 31841561, 2019).
pancreatic cancer (1 paper, 2023). "The associations of ZNF503 acting as an essential regulator have been reported during the developmental process and tumor initiation with multiple carcinomas, but not in pancreatic cancer." (PMID 38049855, 2023).
cancer (6 papers, 2016 to 2024). A tumor composed of atypical neoplastic, often pleomorphic cells that invade other tissues. "The zinc finger protein ZNF503, which plays a positive role in cancer cell growth and invasion, was found to be a novel target candidate of miR-340-5p: the 217–224 position of the ZNF503 3′-UTR was complementary to the seed sequence of miR-340-5p." (PMID 31160893, 2019). "Given the ability of ZFP91, ZNF503, and ZC3H18 to interact with nucleic acids and their known links to cancer, we focused on the 3 ZFPs." (PMID 31841561, 2019). "We also detected differentially methylated regions in cancer-related genes, such as CMYA5, TSLP, ZNF503, and ZNF217, which suggest that the methylation status of these genes may be involved in tumorigenesis or cancer progression." (PMID 34527193, 2021).
tumor (5 papers, 2017 to 2024). "For instance, gene ZNF503 encodes a transcriptional repressor that may regulate genes that drive tumour cell proliferation." (PMID 38778183, 2024). "The results indicated that ZNF503 expression was significantly upregulated in NSCLC tissues compared with adjacent non-tumor tissues." (PMID 31160893, 2019). "However, whether ZNF503 could rescue the anti-tumor effect of NCI-H1650 cell remains unclear." (PMID 31160893, 2019).
infection (1 paper, 2018). The state of being infected such as from the introduction of a foreign agent such as serum, vaccine, antigenic substance or organism. "Transcription factors, such as ZNF503, ZNF283, DYM, and OTX1, that control genes involved in antiviral defense may affect downstream targets at later infection stages." (PMID 29997306, 2018).
ZNF503 also shares sentences with these, for which no sentence is quoted: coloboma (1 paper); depression (1); endometrial cancer (1); gastric cancer (1); liver carcinoma (1); neuroblastoma (1); non-small cell lung carcinoma (1); pulmonary fibrosis (1).